VWF (von Willebrand factor)
Diseases named in the same sentence as VWF in open-access papers (continued):
Sharing a sentence is not in itself a finding about the gene and the disease.
diabetes (continued). "The main novelty of this study is that not only the level but also the oxidative modification of VWF is strongly associated with both presence of high molecular weight multimers and thrombotic angiopathies in diabetes." (PMID 23383177, 2013). "In conclusion, the emerging scenario shows that the oxidative stress in diabetes involves also VWF and is associated with increased presence of UL-VWF multimers that are involved in the genesis of major cardiovascular events in this clinical setting." (PMID 23383177, 2013). "In panel studies, exposure to ambient air pollution was associated with increased blood levels of vWF in patients with diabetes." (PMID 20822968, 2010). "PM10 levels were associated positively with increased von Willebrand factor (vWF) only in person with a history of diabetes." (PMID 19630984, 2009). "Notably, elevated vWF levels are associated with inflammation and diseases like arteritis, diabetes, and sepsis." (PMID 41311551, 2025). "Moreover, hyperglycaemia is associated with higher levels of von Willebrand factor (vWF), tissue factor, and reduced fibrinolysis, all of which contribute to the procoagulant state of diabetes." (PMID 40104479, 2025). "Conversely, endothelial cells respond to raised glucose levels (mimicking hyperglycemia) by producing longer WPBs, suggesting a link between long VWF strings and thrombotic manifestations in diabetes, which is often associated with high levels of plasma VWF and microangiopathy." (PMID 32881285, 2020). "VWF has been associated with an increased risk of incident type 2 diabetes mellitus." (PMID 27787621, 2017). "However, findings from another investigation suggest that the additional explanatory power of VWF (on top of the traditional risk factors, such as hypertension and diabetes) is comparatively low in patients with carotid atherosclerosis." (PMID 24937073, 2014). "Here, we determine whether ADAMTS13 activity and VWF antigen are associated with incident diabetes." (PMID 27787621, 2017). "In one of the study the authors found a positive association between air pollution and inflammatory markers as ICAM-1, VCAM-1 and vWF, suggesting that inflammatory mechanisms may explain the increased risk of air pollution-associated cardiovascular events among persons with diabetes." (PMID 24886318, 2014). "Patients with CAC were older and had higher rates of hypertension, diabetes, hyperlipidaemia, chronic kidney disease, elevated median vWF (227.5 vs 167 IU/dL, p=0.001), D-dimer (370.5 vs 271 ng/mL, p=0.011), and aPWV (8.2 vs 6.0 m/s, p=0.006)." (PMID 41846912, 2026). "This study aimed to investigate the influence of the duration of T2DM on blood glucose levels, glycated hemoglobin (HbA1c), renal function parameters, oxidative stress, and von Willebrand factor (vWf) activity in individuals with diabetes." (PMID 40786424, 2025). "High blood sugar levels over extended periods in diabetics can damage endothelial cells, leading to increased VWF production." (PMID 38394492, 2024). "MASLD’s prothrombotic features are exacerbated by insulin resistance, diabetes, and obesity, manifesting as increased von Willebrand factor, platelet hyperaggregability, hypo-fibrinolysis, and a prothrombotic fibrin clot structure." (PMID 38592258, 2024). "The increase in ROS production accelerated vWf multimers to form endothelial Weibel–Palade bodies in diabetes, and then promoted vWf multimers to be released into the plasma." (PMID 39064844, 2024). "Von Willebrand factor (VWF) is a blood glycoprotein, and elevated VWF is a biomarker of hypertension, diabetes, obesity, and lung cancer." (PMID 36685671, 2023). "The plasma levels of many clotting factors including fibrinogen, tissue factor, coagulation factors Va, VII, VIII, IX, Xa, XI, XII, thrombomodulin, kallikrein, and von Willebrand factor (vWF) are elevated in diabetes." (PMID 35955405, 2022).
diabetes (continued). "Levels of plasma von Willebrand factor, a marker of inflammation that increases in insulin resistance and diabetes, were also determined." (PMID 36364861, 2022). "As a biomarker of endothelial injury, vWF is highly expressed in patients with hypertension, diabetes, and other endothelial dysfunction diseases and poses a great impact on vascular permeability." (PMID 35242298, 2022). "The VWF was significantly increased in insulin-requiring diabetes, which indicated diabetic endothelial injury and damage were the primary mechanisms contributing to an increased occurrence of vascular and cardiac events in diabetic postinfarction patients." (PMID 35966750, 2022). "Topical application of WKYMVm intensified cutaneous wound healing in streptozotocin (STZ)-induced diabetes via the remodeling of von Willebrand factor (vWF)-positive vessels." (PMID 35053347, 2022). "Increased levels of von Willebrand factor in the circulatory system seem to correlate with an increase in platelet activation in diabetes." (PMID 34940563, 2021). "In contrast, there was a significant increase in the vascular marker vWF in skin biopsies from all diabetes (T2DM) groups, which was particularly marked in the painful-DPN group." (PMID 35295465, 2021). "In the animal model, diabetes mellitus led to an increase in the plasma levels of thrombomodulin, VWF and E-selectin in KLK8+/+ mice, which were significantly attenuated in KLK8-/- mice." (PMID 33754057, 2021). "Immunostaining for the vascular marker, vWF, showed increased sub-epidermal staining area in all diabetes groups vs. the HV group." (PMID 35295465, 2021). "Serum VWF can be employed for the early diagnosis of LUAD in patients with type 2 diabetes mellitus." (PMID 33511215, 2021). "A study of 94 patients with non-insulin-dependent diabetes mellitus showed correlation between albuminuria and increased plasma levels of vWF." (PMID 33096906, 2020). "Another link between endothelial dysfunction and platelet hyperaggregation in diabetes mellitus is the increased release of von Willebrand factor, a glycoprotein released into the circulation by secretion from endothelial cells." (PMID 30274207, 2018). "High vWF levels were associated with low BDNF levels even after adjustment for age, gender, low-density lipoprotein (LDL) levels, and the presence of diabetes mellitus." (PMID 29409455, 2018). "To further define the receptors responsible for the enhanced platelet adhesion in diabetes, we perfused whole blood over vWF matrices at 600, 1800, and 5000 s−1." (PMID 29540687, 2018). "Many clotting factors such as I, VII, IX, XII, Kallikrein and von Willebrand factor (VWF) are increased in diabetes." (PMID 29774166, 2018). "We investigated independent and synergistic effects of VWF and ADAMTS13, and explored these associations in the context of prior studies linking ADAMTS13 to diabetes, angiogenesis, and extracellular matrix integrity." (PMID 29615758, 2018). "Univariate logistic analyses revealed that age, male sex, hypertension, diabetes mellitus, triglycerides, HDL cholesterol, BDNF and vWF were significantly associated with the presence of stable CAD." (PMID 29409455, 2018). "There was an interaction between ADAMTS13 activity and VWF antigen level with incident diabetes (p = 0.01)." (PMID 27787621, 2017). "However, VWF may also be associated with diabetes through its prothrombotic effect." (PMID 27787621, 2017). "Like C-reactive protein, VWF is an acute phase reactant, and its level increases in inflammatory and metabolic disorders (i.e., glucose intolerance, diabetes, and obesity)." (PMID 28634421, 2017). "Among the 14 ST3GAL4 SNPs found in ARIC GWAS, the intronic rs2186717, rs7928391, and rs11220465 were associated with VWF levels and with FVIII activity after adjustment for age, BMI, hypertension, diabetes, ever-smoking status, and ABO." (PMID 27584569, 2016).
diabetes (continued). "The low expression of vWF in the 6wDM rats and 12wDM rats indicates that the vasa nervorum of the rats were damaged by the diabetes." (PMID 27057201, 2016). "VWF: CB, PAD, AB0 categories remained significantly associated with the OPG levels after adjustment for diabetes, hypertension, MI, CAD, anti-hypertensive, anti-coagulant drugs, statin and fibrate usage." (PMID 27387019, 2016). "Among covariates known to affect VWF levels in the circulation, diabetes and hypertension were more common in subjects with type B blood." (PMID 26244499, 2015). "Elevated VWF has been found in patients with type 1 diabetes mellitus (DM1) and has been identified as a predictive biomarker of micro and macroangiopathy in these patients." (PMID 26168189, 2015). "Further work on the specificity and sensitivity of VWF:act and VWF-bound carbonyl level is therefore required to ascertain their role as prognostic biomarkers for thrombotic vasculopathies in type 2 diabetes mellitus." (PMID 23383177, 2013). "The plasma levels of many clotting factors, including fibrinogen, factor VII, factor VIII, factor XI, factor XII, kallikrein, and von Willebrand factor are elevated in diabetes." (PMID 21297995, 2011). "The patients with diabetes have increased levels of von Willebrand factor, which correlates with vascular complications; a correlation between insulin resistance and increased concentration of von Willebrand factor has also been demonstrated." (PMID 20112471, 2009). "Plasma levels of ADAMTS-13 and von Willebrand factor (VWF) in controls amongst the different binary variables examined [i.e. according to sex, smoking, diabetes, and the taking of medication for high blood pressure (BP) or high cholesterol]." (PMID 18194418, 2008). "In controls there was no significant age-/sex-adjusted difference (P > 0.05) in mean VWF by sex, ever-smoking status, diabetes status, or use of medication for high blood pressure or for high cholesterol." (PMID 18194418, 2008). "In our study, diabetes reduced vWF IHC staining intensity in skin vessels." (PMID 41511372, 2026). "Hyperglycemia may also induce repression of microRNA-24 (miR-24), leading to increase von Willebrand factor (VWF) expression and secretion in diabetes mellitus." (PMID 40390002, 2025). "Factors of diabetes, myocardial ischemia, old myocardial infarction, and lower extremity atherosclerosis, but not sex, age, coronary heart disease, hypertension, and cardiac function, had significant effect on vWF activity (P < 0.05)." (PMID 37442989, 2023). "To examine the effects of hyperglycemia on the association between ceramide level and annexin A5 expression in the coronary endothelium, we analyze the co-localization of ceramide or annexin A5 to endothelial marker vWF in coronary arteries of mice with streptozotocin-induced diabetes." (PMID 35874544, 2022). "Another prospective study of 631 patients 50–75 years-old showed that increased vWF plasma levels correlated with cardiovascular and all-cause mortality, in patients with and without diabetes mellitus." (PMID 33096906, 2020). "Although these may be the most extreme examples of excess VWF function, many common disorders including hypertension and diabetes are characterized by increased VWF plasma levels." (PMID 32881285, 2020). "PDI content in mice fed with a normal diet plus rutin were significantly reduced compared to the normal diet group, and the rutin-fed mice with diabetes mellitus showed a marked decrease in PDI and VWF levels compared to the diabetes mellitus group (P < 0.01 and P < 0.05 respectively)." (PMID 31437127, 2019). "Proteins with elevated concentrations in both types of diabetes include von Willebrand factor (vWF), (pre)kallikrein, factor V, (activated) factor VII, factor VIII, factor X, factor XI, prothrombin, and fibrinogen (although a study has also reported its reduction in T1DM)." (PMID 31888259, 2019).
diabetes (continued). "Our results suggest that efficient therapy or prevention of microangiopathy through inhibition of the erythrocyte-VWF interaction may decrease the rate of microangiopathic complications in various diseases, such as diabetes, HUS and sickle cell disease." (PMID 30026593, 2018). "Additionally, the present study further suggested that low BDNF levels were associated with high vWF levels even after adjustment for age, LDL levels, gender, and the presence of diabetes mellitus." (PMID 29409455, 2018). "If VWF is associated with diabetes through its prothrombotic function, then we would expect ADAMTS13, with its antithrombotic function, to be inversely associated with the risk of diabetes." (PMID 27787621, 2017). "Low ADAMTS13 activity and high VWF levels may exacerbate small vessel disease, which in turn may contribute to the development of diabetes." (PMID 27787621, 2017). "In previous studies of Sjögren's syndrome, a chronic autoimmune disease in which the body’s white blood cells destroy the exocrine glands, a relationship between MUC5B, von Willebrand factor and diabetes was suggested, indicating a potential role of MUC5B in cardiovascular complications of T2D." (PMID 28346466, 2017). "Plasma levels of vWF are determined by genetic factors (ABO blood groups and vWF mutations) and by non-genetic factors (i.e. aging, impaired nitric oxide production, inflammation, free radical production and diabetes)." (PMID 28570705, 2017). "The higher diabetes risk associated with elevated copeptin remained after adjustment for WC, lifestyle characteristics, social class, renal function (eGFR), use of antihypertensive treatment, statin use, systolic BP, GGT, triglycerides, CRP, and vWF." (PMID 26158609, 2015). "Our data suggests that LGALS3 may protect against thrombus formation in diabetes by suppressing vWF expression in the endothelium." (PMID 26047815, 2015). "Finally, the multivariate model for the whole study population showed that vWF, PAI-1, fibrinogen and diabetes mellitus were the independent predictors of t50% (R2 = 0.58, p < 0.001) whereas vWF was the only independent predictor of Ks (R2 = 0.22, p < 0.001)." (PMID 23086579, 2013). "For participants with normal glucose levels, all haemostatic variables were significantly associated with incident diabetes in the univariate analysis (tPA: OR = 2.43, 95% CI 1.50-3.91; PAI-1: OR=2.66, 95% CI 1.66-4.25; tPA/PAI-1 complex: OR=3.23, 95% CI 1.93-5.41; VWF: OR=1.66, 95% CI 1.13-2.46)." (PMID 23249721, 2012). "The univariate conditional logistic regression analysis showed a significantly increased risk of incident T2DM for family history of diabetes, hypertension, systolic and diastolic blood pressure, FPG, 2hPG, BMI, triglycerides, CRP, tPA, PAI-1, tPA/PAI-1 complex, and VWF." (PMID 23249721, 2012). "For participants with elevated glucose levels, all haemostatic variables were significantly associated with incident diabetes in the univariate analysis (tPA: OR=3.05, 95% CI 2.02-4.61; PAI-1: OR=2.20, 95% CI 1.57-3.07; tPA/PAI-1 complex: OR=4.80, 95% CI 2.90-7.92; VWF: OR=1.86, 95% CI 1.35-2.58)." (PMID 23249721, 2012). "Renal impairment not only delayed the clearance of cytokines, but elevated levels of von Willebrand factor (vWF), adding to both exaggerated inflammatory response and pro-coagulable state; further exacerbated by added vasodynamic insults incited by pre-existing diabetes or hypertension." (PMID 39854588, 2025). "In this family, additional disorders that may be associated with FVIII/VWF increase were reported, including the following: obesity (II-8, II-3, II-9), overweight (II-2, II-5, III-5), diabetes (II-8, II-2, II-3, II-5), dyslipidemia (II-8), atrial fibrillation (II-3), tumor and hypertension (II-5)." (PMID 37762470, 2023).
diabetes (continued). "Our data further demonstrate that, in mice under either control condition or with streptozotocin-induced diabetes, ASM gene deletion causes a decrease in the co-localization of ceramide with vWF, which correlates well with a concomitant decrease in the co-localization of annexin A5 with vWF." (PMID 35874544, 2022). "In our study, EPL reduced vWF exocytosis in both STZ and NORM rats, highlighting a link between elevated ALDO levels and vWF release in diabetes." (PMID 41511372, 2026). "The intravitreal administration of ADAMTS13 attenuates diabetes-induced BRB breakdown, the downregulation of VE-cadherin and β-catenin, and the upregulation of VWF, CD41, phospho-ERK1/2, HMGB1, VCAM-1, and ICAM-1." (PMID 39851513, 2025). "Patients with highest quartile of VWF or lowest quartile of ADAMTS13 had an increased age, cardiovascular disease, diabetes mellitus and an increased CRP as compared with highest quartile of VWF or lowest quartile of ADAMTS13, respectively." (PMID 34134634, 2021). "The results indicated that VWF and PDI levels in mice in the diabetes group were higher than those observed in the normal diet group, with the difference being statistically significant (P < 0.05)." (PMID 31437127, 2019). "Up-regulation of proinflammatory cytokines leads to disturbances in the normal function of the vascular endothelium reflected by increased secretion of endothelium-derived products such as vWF and PAI-1, which have been shown to be predictive of diabetes." (PMID 26158609, 2015). "Univariate logistic regression analysis revealed that the following were all associated with CAD: a decrease in platelet adhesion after GPIb inhibition; VWF:CB activity; smoking; HDL cholesterol values of <1.0 mmol/L for males and <1.2 mmol/L for females; diabetes mellitus; and male sex." (PMID 39335520, 2024). "Logistic regression analysis showed that vWF activity was significantly related with atherosclerosis of lower limbs and old myocardial infarction, but not significantly related with diabetes and myocardial ischemia." (PMID 37442989, 2023). "Patients with diabetes mellitus (DM) had higher VWF:Ag levels than those without DM in the ASCET study." (PMID 36531725, 2022). "First, despite rigorous adjustment for known determinants of VWF and ADAMTS13, residual confounding may still exist, in particular with respect to other factors involved in hemostasis, diabetes, or possibly angiogenesis and extracellular matrix stability." (PMID 29615758, 2018). "In contrast to findings for VWF antigen, low ADAMTS13 activity was associated with cognitive decline and dementia risk throughout the 15-year follow-up in individuals without (pre-)diabetes." (PMID 29615758, 2018). "Adherence to the ‘high-sugar’ dietwas also significantly associated with age and intake of total energy and inverselyassociated with prevalent diabetes, glucose, HDL and CRP, but not significantly associatedwith SBP or vWF." (PMID 27620002, 2016). "Hence, the increase of ROS production in diabetes can accelerate the secretion of VWF multimers from endothelial WPB, favouring the release of large VWF multimers (UL-VWF) into the circulation, as indeed shown in this study." (PMID 23383177, 2013). "It was found that the number of vWF microvessels in the boundary area of ischemic brains was reduced in diabetic mice compared with control (−46.5%, p < 0.01), which was significantly increased in 4-week AKG treated diabetic mice (+42.9%, p < 0.01 vs. Diabetes)." (PMID 41181587, 2025). "In another study, metformin was shown to significantly reduce the levels of sVCAM-1, von Willebrand factor (vWF), tissue-type plasminogen activator (t-PA), plasminogen activator inhibitor-1 (PAI-1) and soluble intercellular adhesion molecule-1 (sICAM-1) in patients with type 2 diabetes mellitus." (PMID 33801956, 2021).